ULK1 (unc-51 like autophagy activating kinase 1)
Diseases named in the same sentence as ULK1 in open-access papers (continued):
Sharing a sentence is not in itself a finding about the gene and the disease.
tumor (continued). "Reducing ULK1 expression and its mediated mitophagy can mitigate the tumor-promoting effect of WTAP overexpression." (PMID 38286802, 2024). "Combined inhibition of KRASG12C and ULK1/2 decreases tumor initiation and increases survival in KL genetically engineered mouse (GEM) models." (PMID 39213022, 2024). "Inhibition of KRASG12C and ULK1/2 reduces tumor burden in a KP genetically engineered mouse (GEM) model." (PMID 39213022, 2024). "Our results show that ULK1 knockdown with siRNA slightly enhances tumor cell proliferation in colony formation and cell proliferation assays." (PMID 39215364, 2024). "Correlations between ULK1 tumour expression levels and clinical parameters are therefore very difficult to interpret." (PMID 38910881, 2024). "Our previous high-throughput screening results indicated that depletion of ULK1 significantly increased the sensitivity of tumor cells to MDM2 inhibitors and induced classical pyroptosis in these cells." (PMID 39215364, 2024). "We found that ULK1 knockout tumors were more sensitive to APG-115 than ULK1 wild-type tumors, with a more significant reduction in tumor volume and a lower weight." (PMID 39215364, 2024). "The inhibitory effect of AdipoRon on tumor growth was significantly attenuated when AdipoR2 and ULK1 were silenced." (PMID 39349421, 2024). "ERK1/2 and ULK1, being widely expressed, hold critical functions in various cell types, including T and tumor cells." (PMID 38447147, 2024). "Here, we demonstrated that increasing ULK1 expression through USP10 upregulation rendered OS cells more susceptible to autophagy and tumor development." (PMID 39218913, 2024). "Autophagy inhibition using small molecule inhibitors of ULK1 or PIKfyve was shown to increase responses to ICB in tumor‐bearing mice." (PMID 38506049, 2024). "Collectively, our results showed that USP10 stimulates OS autophagy and tumor progression by upregulating the GSK3β-ULK1 axis." (PMID 39218913, 2024). "Next, we evaluated the effect of ULK1 overexpression on autophagy and tumor progression in 143B and U2OS cells with GSK3β knockdown." (PMID 39218913, 2024). "To further investigate the effect of ULK1 knockout on the effect of MDM2i in vivo, we subcutaneously implanted tumor cells with ULK1 knockout in nude mice and began treating the mice with APG-115 every two days from day 4 after cell implantation." (PMID 39215364, 2024). "In non-tumor settings, carbamazepine is known to affect ULK1 phosphorylation and thus induce autophagy." (PMID 38446332, 2024). "Our study suggests that pharmacological inhibition of ULK1/2 kinase activity starting at tumor initiation also significantly reduces growth of KRASG12C/LKB1null lung tumors." (PMID 39213022, 2024). "For example, SLLN-15 (an oral selenopurine molecule), LYN-1604 (a ULK1 agonist), and flubendazole exert anti-tumor effects by inducing autophagy." (PMID 38355608, 2024). "NEDD4L also acts as a tumor suppressor and negatively regulates autophagy initiation via destabilizing ULK1 and ASCT2." (PMID 36918822, 2023). "Taken together, these data indicate a direct correlation between the axis of Lon-ULK1 and mitophagy on cell survival and cancer progression under hypoxia condition in the tumor microenvironment." (PMID 36927870, 2023). "We observed that pharmacological inhibition of autophagy-stimulating protein kinase ULK1 or RNA interference-mediated knockdown of autophagy mediator ATG12 significantly sensitized tumor cells to erastin treatment in 2D culture." (PMID 37658069, 2023). "LncRNAs have been reported to affect autosis in tumor cells by regulating the ULK1 complex and mTOR signaling pathway." (PMID 37313458, 2023). "Overexpression of lncRNA H19 inhibits mTOR phosphorylation and promotes ULK1 phosphorylation, thereby inhibiting the development of autosis and promoting tumor cell proliferation." (PMID 37313458, 2023).
tumor (continued). "Sox2OT‐V7 can promote autophagy of tumour cells through the Sox2OT‐V7/miR‐22‐3p/ULK1 axis and Sox2OT‐V7/miR‐142‐5p/ULK1, ATG4A and ATG5 axis, mediating drug resistance to DOX." (PMID 37837401, 2023). "Aside from affecting tumor angiogenesis, copper regulates autophagy through ULK1 and ULK2, as well as promoting tumor formation, growth, and metastasis." (PMID 36874011, 2023). "This study assessed the expression levels of various mitophagy regulators in normal and PAAD tissues, revealing that a majority of them were significantly upregulated in the tumour samples, except ULK1." (PMID 35938160, 2022). "In future studies, we will cooperate with clinical laboratories to further clarify the correlation between the expression of TMEM189, ULK1, and autophagy in different tumor patients." (PMID 35393404, 2022). "It was demonstrated that an aqueous extract of clove can inhibit tumor growth by activating the AMPK/ULK1 pathway." (PMID 36291728, 2022). "The deletion of ATG5 or ULK1 induced a decreased expression of genes involved in the cell cycle and/or replication, supporting the suggestion that autophagy is required for tumor cell expansion." (PMID 35884522, 2022). "The role of ULK1/2 and autophagy in cancer biology is controversial and depends on the specific tumor type and the stage of the disease." (PMID 36291728, 2022). "Further, in pancreatic cancer cells, NEDD4 prevents autophagy activity under metabolic stress by decreasing mitochondrial function and limiting tumor development by destabilizing an autophagy protein, ULK1, and a glutamine transporter, ASCT2." (PMID 36293239, 2022). "To find out the impact of ULK1 R170me2s on tumor development, we intracranially injected athymic nude mice with WT LN229 cells or LN229 cells with knockin expression ULK1 R170K." (PMID 35246531, 2022). "ULK1 expression in paired HCC and para-cancerous tissues displayed a significant association with the tumor size after sex, age, histologic grade, cirrhosis and tumor, nodes, and metastases (TNM) adjustment." (PMID 35252196, 2022). "ULK1 works in brain iron accumulation and regulates the autophagy-mediated cell survival of brain-metastasized tumor cells." (PMID 36248975, 2022). "As a core regulator of autophagy, mTOR inhibition can initiate autophagy in tumour cells by activating the ULK1 complex and further activating the type III PI3K complex." (PMID 36042213, 2022). "The results of protein interaction analysis in Pathway Common also showed that MAPK upstream kinases (MAP3K3, MAP3K5), ERBB3 and ULK1, which are important for tumor cell growth and proliferation, can bind to NEDD4L." (PMID 34539897, 2021). "AMPK activation by STGPT induced autophagy by activating ULK1 at Ser317, thereby decreasing tumor cell survival." (PMID 35095479, 2021). "Consistently, the ULK1 inhibitor SBI-0206965 determines tumor growth arrest in numerous cancers, such as neuroblastoma, renal carcinoma, and NSCLC." (PMID 34830777, 2021). "Difference in methylation levels of Beclin-1, bcl2, LC3 and ULK1 genes in tumor samples compared to normal tissues were analyzed." (PMID 33773561, 2021). "Given that ULK1 activation initiates autophagy and autophagy induction is exhibited by many tumors, elevated ULK1 expression is a feature of human HCC and is associated with tumor size and reduced survival time." (PMID 34829868, 2021). "To evaluate the fundamental role of ULK1/2 on PKM2 expression in vivo, we examined PKM2 expression using immunohistochemistry (IHC) in subcutaneous tumor xenografts arised from nude mice that were inoculated with S-1 cells bearing ULK1, ULK2 or ULK1/2 shRNA." (PMID 34345207, 2021). "As cytotoxic therapy induces elevated ROS levels and triggers the ULK1 pathway to activate protective autophagy and mitophagy, dual targeting of NUAK1 and ULK1 by MRT68921 can be beneficial in tumour management." (PMID 34706732, 2021).
tumor (continued). "ULK1-mediated autophagy can either promote tumor progression or suppress tumor growth, as well as confer drug resistance." (PMID 33670113, 2021). "Functionally, the silencing and deletion of ULK1 in HepG2 and primary human cells suppressed tumor cell proliferation and increased the therapeutic effects of sorafenib in vitro and in vivo." (PMID 34829868, 2021). "BBR-mediated apoptosis blocks the AMPK/mTOR/ULK1 pathway and decreases tumor growth in glioblastoma polymorphic (GBM) cells in vivo." (PMID 34885950, 2021). "Autophagy activation observed previously in tumor-bearing mice was recapitulated in cancer patients including increase of LC3b and Gabarapl1 as well as active ULK-1, which were accompanied by reduced p62 as expected." (PMID 34950660, 2021). "In these mouse models, essential autophagy genes, such as ATG5, ATG7, ATG13 or ULK1, are deleted in genome of tumor cells that arise spontaneously in the context of a normal tumor microenvironment and functional immune system." (PMID 32308763, 2020). "It has been shown that ULK1 can either promote or inhibit tumor growth through protein–protein interactions and post-translational modification-mediated autophagy in nutrient-deficient environments." (PMID 32033142, 2020). "The loss of COX5B-mediated facilitation of bioenergy production resulted in AMPK activation, leading to repression of UHMK1 (an oncogene) expression and induction of ULK1 (a tumor suppressor) via unidentified mechanisms." (PMID 32580279, 2020). "Herein, the potential antitumor activities of a dual NUAK1/ULK1 inhibitor MRT68921 were evaluated in both tumor cell lines and animal models." (PMID 32873786, 2020). "In this review, we summarized the biological function of ULK1 in tumors with respect to its potential as a target for tumor therapy and its impact on the occurrence of drug resistance by mediating autophagy in tumor cells." (PMID 32033142, 2020). "Protein expression of ULK1 and Beclin-1, and the ratio of LC 3 II/I were significantly reduced in the tumor tissue of BJE-H group." (PMID 32411003, 2020). "More interestingly, the protein levels of NEDD4L and ULK1 or ASCT2 were inversely expressed in both xenograft tumor and tumor from spontaneous PDAC mouse model, KPC mice." (PMID 31959741, 2020). "Together, our study identifies Exo70 as a substrate of ULK1 that inhibits cancer metastasis, and demonstrates that two counteractive regulatory mechanisms are well orchestrated during tumor cell invasion." (PMID 31913283, 2020). "We propose a novel mechanism showing that cancers expressing low levels of NEDD4L enhance autophagy and mitochondrial metabolism via deregulating the protein activity of ULK1 and a glutamine transporter, and so promote tumor development." (PMID 31959741, 2020). "Regulation of ULK1 plays a fundamental role by influencing cell growth and the development of drug resistance in tumor cells." (PMID 32033142, 2020). "Our study delineates a molecular pathway by which ULK1 regulates tumor invasion through direct phosphorylation of Exo70, and also reveals a counteractive regulatory mechanism that functions during tumor invasion." (PMID 31913283, 2020). "Emerging evidence demonstrates that the AMPK/mTOR/ULK1 signaling pathway is a critical regulator of tumor autophagy, and participates in the progressions of numerous tumor types." (PMID 33292257, 2020). "Similar to the results from xenograft mouse, the PDAC tumor regions with higher levels of ULK1 also showed relatively higher levels of Ki67 staining." (PMID 31959741, 2020). "In this study, we proposed an effective combination strategy of dual inhibition of NUAK1 and ULK1 kinase activities, which was proved to have a synergetic cytotoxic effect on tumor cells, which promotes apoptosis and elevated levels of ROS." (PMID 32873786, 2020). "As the levels of ULK1 were induced, Ki67 intensities were significantly increased in shNEDD4L cell-driven tumors compared to those in shCTL tumor." (PMID 31959741, 2020).
tumor (continued). "Protein analysis of matched tumor lysates showed diminished phosphorylation of S6 and ULK1, indicating inhibition of mTORC1." (PMID 32656088, 2020). "Tumor cells exhibited a reduced autophagic flux with pharmacologic and genetic inhibition of ULK1 or VPS34." (PMID 31515514, 2019). "As a sponge of miR-20a-5p, PVT1 can increase the expression of unc-51-like kinase 1 (ULK1), which promotes autophagy in tumor cells, thereby providing sufficient energy for tumor growth." (PMID 31380270, 2019). "In a similar manner, knockdown of ULK1 during hypoxia results in cell death, implying that tumour cells, which are often present in hypoxic environments in vivo, rely on autophagy for their survival in an ULK1-dependent manner." (PMID 29233870, 2017). "Again, Ulk1 IHC intensity was significantly higher in the cancer tissues (“Tumor”) than that in the surrounding normal epithelial tissues (“Normal”)." (PMID 28410240, 2017). "Knock down of ATM, AMPKα or ULK-1 reduced the ability of [curcumin + sildenafil] to induce autophagosome formation and tumor cell death." (PMID 29245915, 2017). "In agreement with our ULK-1 S317 data, knock down of AMPK also significantly reduced the ability of [pemetrexed + sildenafil] to increase autophagosome levels and to cause tumor cell death." (PMID 27903966, 2017). "Because ULK1, the key regulator of autophagy, is reduced, it becomes difficult for tumor cells to up-regulate autophagy and restore survival." (PMID 26593251, 2016). "For IHC staining, the positive ULK1 protein immunoreactivity was mainly detected in the cytoplasm pattern of tumor cells." (PMID 25714809, 2015). "Given the role of autophagy in modulating tumor immunity, we next examined whether Ulk1 deletion alters immune cell composition within the TME." (PMID 41408407, 2025). "Furthermore, western blotting analysis of tumor tissues showed that PCA induced the up-regulation of p-ULK1, p-AMPK and formation of LC3B-II, as well as the down-regulation of p-S6K, which was consistent with in vitro results." (PMID 40260299, 2025). "Moreover, the secreted levels of G-CSF and Ccl2 were notably reduced, but GM-CSF levels were significantly elevated in in CM from Ulk1 KO cells, indicating that Ulk1 determines to regulate tumor-intrinsic G-CSF, Ccl2 and GM-CSF secretion oppositely." (PMID 41408407, 2025). "Moreover, mice bearing Ulk1 KO tumors showed significantly extended survival compared with control KPC tumor-injecting mice." (PMID 41408407, 2025). "Notably, TPP+ conjugates such as 3-carboxy-proxyl nitroxide (Mito-CP) and Metformin (Mito-Met10) have been shown to directly activate ULK1, a key initiator of mitophagy, thereby promoting an anti-tumor mitophagy response." (PMID 40750884, 2025). "Furthermore, our experiments showed that the USP10-GSK3β-ULK1 axis was involved in autophagy and tumor progression in OS." (PMID 39218913, 2024). "Several studies focusing on ULK1 have found its dual role in suppressing or promoting tumor growth." (PMID 38976168, 2024). "Interestingly, ULK1 was a sort of serine/threonine kinase, which was a well‐known autophagic initiator, extensively involved in human diseases especially tumours." (PMID 38572589, 2024). "In addition, combined inhibition of KRASG12C plus ULK1/2 leads to decreased cell proliferation and tumor growth." (PMID 39213022, 2024). "Additionally, in genetically engineered mouse models of KRASG12C-driven NSCLC, inhibition of either KRASG12C or ULK1/2 decreases tumor burden and increases mouse survival." (PMID 39213022, 2024). "For example, activation of ULK1 may enhance the anti-tumor effect of macrophages, whereas by inhibiting BAG3, the control of AML by immune cells may be enhanced." (PMID 39650664, 2024). "The expression of BECN1, ATG3, and ULK1 significantly altered between normal and tumor patients." (PMID 37790849, 2023).
tumor (continued). "Furthermore, we found that higher level of STK38 indicated poor prognosis in our dataset and TCGA database, suggesting that Caprin-1 promotes tumor growth through ULK1/STK38-dependent autophagy." (PMID 38082307, 2023). "Future studies are required to investigate whether CHAF1B interacts with ULK1 in these solid tumors and to further elucidate the potential biological role of this complex in various tumor types." (PMID 37377894, 2023). "Specifically, assessing whether inhibition of ULK1 affects CHAF1B's protumorigenic role in other tumor types may exhibit important clinical significance." (PMID 37377894, 2023). "However, when the concentration of copper at the tumor site is abnormal, copper can regulate autophagy through ULK1 and ULK2, and control protein quality through UBE2D2, which in turn affects the growth and progression of the tumor." (PMID 36891559, 2023). "Additionally, both the genetic and pharmacological inhibition of ULK1 led to the inhibition of the proliferation and invasion of human HCC cells, and Ulk1 deletion abrogated the tumor growth in a xenograft mouse model." (PMID 35252196, 2022). "Both inhibition and activation of ULK1 show significant effects on tumor treatment." (PMID 35963853, 2022). "In addition, in the process of chemotherapy, the low level of ULK1 will inhibit autophagy activity in tumor cells, which will increase their tolerance to chemotherapeutic drugs, so as to promote the invasion and growth of cancer cells." (PMID 35692501, 2022). "Immunohistochemical staining with validated anti-ULK1 R170me2s or anti-ULK1 pT180 antibody revealed that ULK1 R170K mutation abolished ULK1 R170me2s, and reduced the phosphorylation of ULK1 T180, Atg13 S355, and Beclin 1 S15 in the tumor samples derived from the mice in normoxia condition." (PMID 35246531, 2022). "According to the results of the experimental validation of the samples, three genes (SDHB, ULK1, and CCS) had the highest risk scores and the same trend of the gene expression between tumor and normal tissues when compared with DEGs in TCGA, which means that our model has consolidated verification." (PMID 36505872, 2022). "Furthermore, in LKB1 mutant tumor models, ULK1 suppression and PD-1 antibody inhibition act as co-promoters of the effector T cell growth and tumor regression." (PMID 36300110, 2022). "Moreover, we for the first time demonstrated that miR-1262 acts as a novel tumor suppressor via suppressing expression of oncogene ULK1 in GCA." (PMID 33442421, 2021). "Moreover, the expression of LC3 and ULK1 were increased in the xenograft tumor tissues treated with DSF/Cu group by Western blot." (PMID 34887757, 2021). "Six overall survival associated genes (ENPP2, ULK1, CP, LURAP1L, HIC1, AKR1C1) were selected to build survival model, of which hub gene AKR1C1 was with high expression and low ferroptosis level in NSCLC tumor." (PMID 34702254, 2021). "The combination of a Unc-51 Like Autophagy Activating Kinase 1 (ULK1) inhibitor, MRT68921, with an anti-PD-1 monoclonal antibody can increase antigen presentation and therefore restore anti-tumor immunity, by compensating for LKB1 loss, leading to KRAS/LKB1 co-mutant tumor regression." (PMID 34944952, 2021). "Many studies have indicated that compounds that directly or indirectly target ULK1 could be used for tumor therapy." (PMID 32033142, 2020). "Interestingly, ULK1 inhibitors have also shown their efficacy in limiting cancer growth; thus, it is possible that some of the anti-tumor effects of ULK1 inhibitors are mediated through their effect on the MVA pathway." (PMID 33083385, 2020). "Moreover, the deletion of Atg5 or Atg7, atg13 or Ulk1, Fip200, and Atg7 decrease tumor progression in various oncogene-driven cancer types." (PMID 33260729, 2020). "Thus, the combined inhibition of NUAK1 and ULK1 showed a strong synergistic effect in different tumor types." (PMID 32873786, 2020).